MAPT (microtubule associated protein tau)
Diseases named in the same sentence as MAPT in open-access papers (continued):
Sharing a sentence is not in itself a finding about the gene and the disease.
Parkinson disease (continued). "Progressive supranuclear palsy is an akinetic-rigid form of parkinsonism caused by intracerebral accumulation of the hyperphosphorylated microtubule-associated protein tau (MAPT)." (PMID 34512258, 2021). "A causal role of tau was established in neurodegeneration when dominant mutations in MAPT were determined to cause familial Frontotemporal dementia with Parkinsonism linked to chromosome 17 (FTDP-17)." (PMID 33830330, 2021). "For example, cryptic splice site usage resulting in exon 7 skipping of PINK1 causes early-onset Parkinson’s disease, while increased inclusion of exon 10 in MAPT causes frontotemporal dementia with parkinsonism." (PMID 33414398, 2021). "Common genetic variation of the Apolipoprotein E (APOE) and micro-tubule associated protein tau (MAPT) loci have been linked to cognitive decline and dementia in Parkinson's disease, although studies have yielded mixed results." (PMID 33613437, 2021). "A positive family history of parkinsonism or dementia resulted extremely frequent in MAPT mutation carriers (7 out of 9 subjects, 78% of the total MAPT subgroup), confirming MAPT mutations as highly penetrant." (PMID 33467748, 2021). "Frontotemporal dementia and parkinsonism linked to chromosome 17 (FTDP-17) due to MAPT mutation is a heterogeneous genetic neurodegenerative disorder associated with familial frontotemporal dementia (FTD) and/or parkinsonism." (PMID 34466673, 2021). "Mutations in MAPT gene cause multiple neurological disorders, including frontal temporal lobar degeneration and parkinsonism." (PMID 34805172, 2021). "She had a pathogenic mutation in MAPT (E10 + 16 C > T mutation) and declined clinically with features of Parkinsonism and mutism with death at age 64 from end-stage dementia." (PMID 34794500, 2021). "Another interesting point linking α-synuclein to tau is that mutations in the SNCA and MAPT genes can both lead to neurodegenerative disorders characterized by parkinsonism." (PMID 32655357, 2020). "Since that time, over 60 MAPT mutations have been discovered, with the majority presenting with clinical features of behavioral change and/or parkinsonism." (PMID 31870644, 2020). "MAPT mutations can be more variable depending on the mutation, but often manifest themselves with parkinsonism accompanied by behavioural and personality disturbances." (PMID 32722332, 2020). "Mutations in MAPT were first associated with frontotemporal dementia and parkinsonism linked to chromosome 17." (PMID 31428316, 2019). "Previously, we found that familial Parkinson’s disease-linked human mutant A53T αS causes aberrant localization of the microtubule-associated protein tau to postsynaptic spines in neurons, leading to postsynaptic deficits." (PMID 31168644, 2019). "For instance, ESE, ESS and 5’ SS mutations in the exon 10 of the MAPT gene, encoding the microtubule-associated protein Tau, have been identified as the cause of frontotemporal dementia with parkinsonism linked to chromosome 17 (FTDP-17)." (PMID 31671093, 2019). "Parkinsonism in familial FTLD was first described in families with mutations in the microtubule-associated protein tau (MAPT) and progranulin (PRGN) genes." (PMID 29881367, 2018). "Dominantly inherited mutations in MAPT, which encodes Tau protein, cause frontotemporal dementia and Parkinsonism linked to chromosome 17, showing that dysfunction of Tau is sufficient to cause neurodegeneration and dementia." (PMID 30240946, 2018). "This includes the rs541455835 variant at the MAPT locus encoding the Tau protein associated with Parkinson's disease." (PMID 29669022, 2018). "Fifty-eight healthy controls from the Oxford Parkinson's Disease Center Discovery Cohort were screened to identify individuals heterozygous for the MAPT H1 and H2 alleles." (PMID 28689993, 2017).
Parkinson disease (continued). "A symmetric tremorless parkinsonism with axial rigidity and supranuclear gaze palsy has been shown to be highly predictive of progressive supranuclear palsy pathology due to MAPT or, less commonly, C9orf72 mutations." (PMID 28265458, 2017). "Genome wide association studies have identified microtubule associated protein tau (MAPT) H1 haplotype single nucleotide polymorphisms (SNPs) as leading common risk variants for Parkinson’s disease, progressive supranuclear palsy and corticobasal degeneration." (PMID 29084565, 2017). "In summary, our results begin to dissect the complex interplay of different risk factors related to the MAPT locus in its influence of aging-related parkinsonism, mainly through an effect that is manifested clinically as bradykinesia." (PMID 27458716, 2016). "We observed that the levels of expression of only one of the MAPT isoforms expressed in the human brain were significantly associated with global parkinsonism and bradykinesia scores." (PMID 27458716, 2016). "The MAPT H2 haplotype was associated with lower total MAPT expression (p = 1.2x10-14) and global parkinsonism at both study entry (p = 0.001) and proximate to death (p = 0.050)." (PMID 27458716, 2016). "Analysing MAPT alternative splicing, the expression of 1N/4R isoform was inversely associated with global parkinsonism (p = 0.008) and bradykinesia (p = 0.008)." (PMID 27458716, 2016). "A common polymorphism in MAPT has been linked to dementia in Parkinson’s disease and patients carrying the H1 MAPT polymorphism make more errors in difficult spatial rotation tasks, and show reduced parietal cortex activity." (PMID 27412389, 2016). "In H114, two non-synonymous mutations in MAPT (microtubule-associated protein tau), which was associated with inheritable Parkinson’s disease were identified." (PMID 28053828, 2016). "MAPT H1 and H2 major haplotypes* and MAPT subhaplotype H1c** association with global parkinsonism and motor components at baselinea and lastb measurements." (PMID 27458716, 2016). "In our data, we observed an association of the MAPT H2 haplotype with greater global parkinsonism and its component measures of bradykinesia and gait score, but not rigidity or tremor, at the baseline measurement of each subject." (PMID 27458716, 2016). "Overall, our results suggest that age and H2 are associated with higher parkinsonism score and decreased total MAPT RNA expression." (PMID 27458716, 2016). "The clinical phenotype of patients with MAPT mutations can be divided into a dementia-dominant type and a parkinsonism-dominant type." (PMID 26388768, 2015). "The common H1 haplotypic variant of the microtubule-associated protein tau gene (MAPT) has been related to an increased risk for Parkinson's disease (PD)." (PMID 25577413, 2015). "MAPT mutation carriers often present with a very early age of onset bvFTD, associated with parkinsonism, which is a common feature later in the disease course in all types of genetic FTLD." (PMID 26388768, 2015). "The relevance of tau for neurodegeneration has been confirmed by the identification of mutations in the MAPT gene in cases with familial frontotemporal dementia and parkinsonism linked to chromosome 17 (FTDP-17T)." (PMID 26220942, 2015). "This is of particular interest given that the H1 MAPT haplotype has consistently been shown to be the risk haplotype for other neurodegenerative disorders including dementia in Parkinson’s disease." (PMID 25953777, 2015). "It is fascinating to observe that familial cases carrying mutations in the microtubule-associated protein tau (MAPT) or SNCA genes can phenotypically present with a combination of both parkinsonism and dementia." (PMID 25352339, 2014). "While most of the mutations such as P301L and N279K primarily cause familial FTD, other phenotypes such as CBD, PSP and variable extent of parkinsonism have been observed in some patients and families with MAPT mutations." (PMID 25352339, 2014).
Parkinson disease (continued). "The MAPT haplotype H1 (versus H2) not only predisposes to Parkinson’s disease but also Parkinson’s disease dementia, possibly by altering the cortical expression of 4- versus 3-repeat isoforms of tau." (PMID 25080285, 2014). "A second gene linked to cognitive performance and dementia in Parkinson’s disease is the microtubule-associated protein tau (MAPT)." (PMID 25080285, 2014). "Mutations in the MAPT gene also cause a variety of neurodegenerative phenotypes including parkinsonism." (PMID 25352339, 2014). "The key clinical features of MAPT mutations are behavioral changes, semantic impairment, episodic memory decline, and parkinsonism." (PMID 23998300, 2014). "The key discovery directly involving tau protein in neurodegeneration and dementia came from the finding that highly penetrant, dominant mutations in the MAPT gene encoding tau cause an inherited form of frontotemporal dementia and parkinsonism." (PMID 24795568, 2014). "Microtubule-associated protein tau (MAPT) is a neuronal protein involved in the pathogenesis of several neurodegenerative diseases including Parkinson’s Disease (PD)." (PMID 24779391, 2014). "The discovery of MAPT mutations in families with hereditary dementia with parkinsonism allowed the unified classification of a group of families with a wide spectrum of clinical and pathological diagnoses." (PMID 23338750, 2013). "The same is true of cases with MAPT mutations and frontotemporal dementia and parkinsonism linked to chromosome 17 (FTDP-17T), some of which can cause an asymmetric, akinetic-rigid syndrome whose initial stages are indistinguishable from PD." (PMID 23938306, 2013). "The first mutations causing FTD with parkinsonism (FTDP-17) were first found in chromosome 17 MAPT, which encodes for the tau protein, critical for microtubule assembly and stabilization in neurons." (PMID 23970926, 2013). "While a number of genome-wide association studies have identified microtubule-associated protein tau as a strong risk factor for Parkinson’s disease (PD), little is known about the mechanism through which human tau can predispose an individual to this disease." (PMID 23494099, 2013). "Variation in this region has been associated with Parkinson's disease (MAPT, PLEKHM1, NSF, c17orf69) progressive supranuclear palsy (MAPT), celiac disease (WNT3), bone mineral density (CRHR1) (NHGRI GWAS catalog) and intracranial volume." (PMID 23544013, 2013). "SNCA and MAPT genes and environmental factors are important risk factors of Parkinson's disease [PD], the second-most common neurodegenerative disease." (PMID 22292029, 2012). "We identified a rare p.A152T variant in MAPT exon 7 in two (of eight) patients with clinical presentation of parkinsonism and postmortem finding of neurofibrillary tangle pathology." (PMID 22595371, 2012). "Different MAPT haplotypes are associated with Parkinson's disease and progressive supranuclear palsy." (PMID 21034472, 2010). "Concurrence of movement disorder characterised by parkinsonism and young-onset dementia should suggest the possibility of a mutation in the gene encoding MAPT." (PMID 19175287, 2009). "MAPT mutation carrier phenotypes demonstrate behavioral changes, dementia, and parkinsonism, with an average disease duration of seven years." (PMID 21416021, 2009). "The H1 haplotype of the MAPT gene had already been associated with the pathogenesis of parkinsonism tauopathies as progressive supranuclear palsy and corticobasal degeneration." (PMID 19558713, 2009). "The association between mutations in the MAPT gene and development of fronto-temporal dementia with Parkinsonism-linked to chromosome 17 (FTLD-17) has paved the way for dysfunctional Tau, being considered sufficient for causing neurodegeneration and dementia even in absence of amyloid pathology." (PMID 36915196, 2023).
Parkinson disease (continued). "The MAPT H1/H2 haplotype, defined by a 900 kb inversion and tagged by numerous SNVs, has been associated with several neurodegenerative diseases, including progress supranuclear palsy, frontotemporal disorders, Parkinson’s disease, and AD24,25,41." (PMID 37886469, 2023). "Parkinsonism may present as the initial symptom in MAPT mutation carriers, particularly individuals with MAPT N279K mutation." (PMID 36051222, 2022). "We then examined whether LRRK2 and Parkin recruitment to damaged mitochondria was impaired in 7 fibroblast lines of FTLD and parkinsonism patients or at-risk individuals with MAPT mutations, obtained from the NINDS human and cell repository." (PMID 34805172, 2021). "In contrast with Europe, parkinsonism is relatively rare in the FTD patients possessing the P301L MAPT mutation or the C9orf72 repeat expansion in China, thus suggesting that genetic heterogeneity is associated with different geographical regions and ethnicities." (PMID 34305575, 2021). "In addition, the MAPT gene, which expresses tau, is implicated in not only Alzheimer’s but also Parkinson’s." (PMID 35002678, 2021). "Notably, prominent parkinsonism was found for the first time in Chinese bvFTD patients with the P301L MAPT and C9orf72 gene mutation, respectively." (PMID 34305575, 2021). "Nonetheless, in patients with an autosomal dominant history of atypical parkinsonism, TBK1 should be part of any atypical parkinsonism gene panel along with MAPT and GRN, and mutations in TBK1 suspected if other family members have ALS (which would not be seen in MAPT or GRN mutations)." (PMID 32980182, 2021). "Moreover, Mapt is a well-known gene encoding the microtubule-associated protein tau and has been implicated in Parkinson’s disease." (PMID 35211476, 2021). "Moreover, dominantly inherited mutations in the microtubule‐associated protein Tau (MAPT) gene, which encodes Tau protein, cause frontotemporal dementia and parkinsonism linked to chromosome 17 (FTDP‐17T)." (PMID 33179866, 2020). "Tracers associated with dopaminergic function were applied in MAPT mutation carriers, especially in the N279K mutation type, which may present with parkinsonism as the first symptom." (PMID 32184751, 2020). "Only two variants have been reported in position +13: the A > G transition in intron 10 of the MAPT gene, associated with familial frontotemporal dementia with parkinsonism, and the C > T transition in FGB gene’s intron 6, associated with congenital afibrinogenemia." (PMID 33245593, 2020). "Moreover, genetic studies have linked variants of the tau gene, MAPT, to susceptibility of developing sporadic PD, and mutations in MAPT are associated with dementia with parkinsonism." (PMID 31667556, 2020). "Several polymorphisms in and around MAPT have been discovered in GWAS of Parkinson’s disease." (PMID 31504236, 2019). "rs8070723 is an intronic A/G SNP (major allele A frequency 0.881, minor allele G frequency 0.119) in MAPT, the gene that encodes the microtubule-associated protein tau, and is associated with Progressive Supranuclear Palsy and with Parkinson’s Disease." (PMID 31001319, 2019). "Using an additive model, we examined the association between the two major MAPT haplotypes and global parkinsonism as well as its four component motor domains: bradykinesia, gait impairment, tremor and rigidity, which are measured at both at baseline and annually thereafter." (PMID 27458716, 2016). "After further adjusting for MAPT total level of expression, this isoform remained associated with global parkinsonism (β = -0.0165, p = 0.012, adjusted for age, sex, study and pathology) and bradykinesia (β = -0.0276, p = 0.011, adjusted for age, sex, study and pathology)." (PMID 27458716, 2016).
Parkinson disease (continued). "In H114, two of the “SNPs with high read-depth” (>30X sequence coverage; ), [chr17: 41400462] and [chr17:41400511], resulted in two non-synonymous mutations in MAPT (microtubule-associated protein tau), which was associated with inheritable Parkinson’s disease." (PMID 28053828, 2016). "Furthermore, the neuroprotective effect of MAPT hypermethylation is somewhat illustrated by the fact that higher methylation in Parkinson leukocytes is associated with late-onset PD." (PMID 26170022, 2015). "Since 1998, when mutations in the microtubule-associated protein tau (MAPT) gene on chromosome 17 were found to cause FTD with parkinsonism, geneticists have been stymied by families with FTD linked to the same region on chromosome 17 but having no MAPT mutations." (PMID 16956414, 2006). "Moreover, the study dissected the complex inverted haplotype of the MAPT (encoding tau) Parkinson’s disease risk locus, identifying putative ectopic regulatory interactions in neurons that may mediate the disease association." (PMID 39500613, 2025). "Though C9orf72, GRN and MAPT mutations most often result in bvFTD, they occasionally result in other neurodegenerative syndromes including primary progressive aphasia, amyotrophic lateral sclerosis, corticobasal syndrome, progressive supranuclear palsy, and parkinsonism." (PMID 39568670, 2024). "Indeed, a constellation of nonspecific motor signs like bradykinesia and ALS-like features such as spasticity, limb weakness, and fasciculations are present in around 40% of MAPT mutation carriers, although less common than the Parkinson’s-like motor phenotype." (PMID 38592608, 2024). "The fact that motor disorders and parkinsonism are typically brought into connection with a MAPT pathogenic variant may be caused by the earlier discovery of MAPT pathogenic variants in people with PSP-like phenotypes, 8 years earlier than GRN6 and 13 years earlier than c9orf72." (PMID 35948443, 2022). "Notably, mutations in the MAPT gene cause variable extents of parkinsonism in affected people." (PMID 28386764, 2017). "However, they may also include neuroplasticity consequences of COMT, APOE and MAPT functional polymorphisms in the context of Parkinson’s disease pathogenesis, or developmental effects even if these diminish with older age (e.g. for COMT)." (PMID 25080285, 2014). "It is particularly difficult to interpret the PD GWAS findings for the MAPT locus, which is the second most strongly implicated region in the US Parkinson Disease GWAS Consortium." (PMID 23071545, 2012). "Variation at the 17q21.31 locus, which contains the gene encoding microtubule-associated protein tau (MAPT), has been associated with neurodegenerative disorders, including Parkinson’s disease (PD)." (PMID 41472865, 2025). "Dominantly inherited mutations in MAPT, the microtubule-associated protein tau gene, give rise to cases of FTD and parkinsonism linked to chromosome 17." (PMID 40044789, 2025). "Mutations in the microtubule-associated protein tau (MAPT) gene, located on chromosome 17, are a well-established cause of FTD with parkinsonism." (PMID 40722695, 2025). "In the following few sentences, we will focus on mutations in the MAPT gene, the Tau gene, that account for 5% of FTD cases and are frequently associated with parkinsonism (FTDP‐17)." (PMID 40387258, 2025). "Genetic FTD linked to MAPT mutations are denoted FTD associated to chromosome 17 (FTD-17), sometimes termed FTDP-17 if parkinsonism is clinically present." (PMID 40771194, 2025). "Mutations in the GBA1 gene are one of the most common risk factors for Parkinson’s disease (PD) besides SNCA, LRRK2, and MAPT." (PMID 38203854, 2024). "FTD-parkinsonism and FTD-ALS are clinical overlaps included in the spectrum of MAPT mutation’s phenotypes." (PMID 37730935, 2024).